IFI16 (interferon gamma inducible protein 16)
Diseases named in the same sentence as IFI16 in open-access papers (continued):
Sharing a sentence is not in itself a finding about the gene and the disease.
infection (continued). "Overall, these results indicate that IDR phosphorylation does not impact the ability of IFI16 to suppress transcription either in vitro or in cells during infection, and that phosphorylation-mediated phase separation of IFI16 specifically promotes cytokine induction." (PMID 37283074, 2023). "We next investigated whether the localization of IFI16 to viral genomes is sustained throughout infection upon the development of nuclear viral replication compartments." (PMID 37283074, 2023). "Post-infection, complexes of IFI16, ASC, and caspase 1 were identified by co-immunoprecipitation." (PMID 35458396, 2022). "In conclusion, despite the limited number of clinical specimens, we demonstrated that IFI16 of PBMCs may sense HBV DNA during the infection." (PMID 34869083, 2021). "Importantly, TRIM22 levels in 7134R infection were comparable to levels observed in mock infection, while levels of the known restriction factor IFI16, are reduced in 7134R infection (lane 3)." (PMID 33524065, 2021). "The tegument protein layer of HCMV encodes a pp65 protein that is important for innate immune evasion (IFI16/cGAS-STING pathway) in the early stages of infection, but pp65 is also a T-cell target antigen and has been explored as a vaccine candidate with limited success." (PMID 34452332, 2021). "Indeed, in both keratinocytes and macrophages, IFI16 cooperates with cGAS for STING activation upon infection." (PMID 33981307, 2021). "Interestingly, nuclear IFI16 can assemble inflammasomes during infection by KSHV and HSV-1, leading to the secretion of proinflammatory interleukins." (PMID 32430029, 2020). "Further studies demonstrated that IFI16 has DNA sensor activity in the nucleus after different types of infections with nuclear-replication DNA viruses, including HSV-1, KSHV, and HCMV, as well as after retrovirus infection, recognizing DNA intermediates of human immunodeficiency virus 1 (HIV-1)." (PMID 33255247, 2020). "We infected the NK92 cell line and primary NK cells with cell-free inocula of HHV-6A, HHV-6B or HHV-7 and evaluated TLR9, STING, and IFI16 pathway expression by Real-Time PCR, Western Blot, immunofluorescence and flow cytometry for 1, 2, 3, and 6 days post-infection." (PMID 32140147, 2020). "Our observation that the US28-dependent downregulation of IFI16 occurred rapidly (within 24 h of infection) may, in part, be attributable to incoming US28 which is functional." (PMID 31796538, 2019). "To determine whether US28 specifically downregulates IFI16 in the context of infection, we compared the expression of this cellular protein in monocytes infected with US28-3XF or ΔUS28." (PMID 31796538, 2019). "However, we did observe a partial downregulation of IFI16 in ΔUS28-infected monocytes at later time points of infection." (PMID 31796538, 2019). "We also analyzed the effect of cellular differentiation on IFI16 expression following infection in mature dendritic cells derived by treating ex vivo CD14+ monocytes with granulocyte-macrophage colony-stimulating factor (GM-CSF)/interleukin-4 (IL-4)/lipopolysaccharide (LPS)." (PMID 31796538, 2019). "The IFI16 expression level was measured at 24 and 48 hours after infection (hpi)." (PMID 31423125, 2019). "In this study, we demonstrated that the p200 family proteins, represented by IFI204, which is well known as an ALR and murine ortholog of IFI16, were markedly induced in bone marrow-derived dendritic cells (BMDCs) after infection by mouse hepatitis coronavirus (MHV)." (PMID 31603949, 2019). "Using the same ChIP promoter primers, we found that 48 hr post-infection (p.i.)with KSHV in IFI16 depleted cells, recruitment of H3K9me3 on lytic pK8, pvIRF2 and pORF63 decreased at least by 0.5-fold (black arrows) while H3K4me3 and H3K27me3 did not change significantly." (PMID 31682228, 2019). "IFI16 is either directly or indirectly targeted by ICP0 during infection." (PMID 30018111, 2018).
infection (continued). "Interestingly, the basal level of IFI16 correlated with induction of ISG54 following infection with HIV+vpx." (PMID 28186168, 2017). "Thus, IFI16 specifically enhanced the capacity of macrophages to sense infection by DNA-containing or −producing viruses." (PMID 28186168, 2017). "We show that IFI16 is specifically required for the innate immune response to transfected DNA and to infection with nuclear and cytosolic DNA viruses, but is dispensable for the response to poly(I:C), in vitro transcribed RNA, and during infection with Sendai virus." (PMID 28194029, 2017). "Thus, during infection with DNA viruses IFI16 localizes to viral factories in both the nucleus and the cytosol, consistent with a role in the detection of foreign DNA in both compartments." (PMID 28194029, 2017). "H2B is critical in KSHV and HSV-1 genome recognition by IFI16 during de novo infection." (PMID 27764250, 2016). "Furthermore, colocalization of H2B+STING PLA spots with IFI16+H2B and BRCA1+H2B spots (yellow spots and red arrows) suggested that the macromolecular complex formed between IFI16+H2B+BRCA1 is in close proximity with STING in the cytoplasm after infection." (PMID 27764250, 2016). "The involvement of IFI16 in early infection has also been investigated for several herpesviruses." (PMID 27782081, 2016). "Models for the mechanisms by which ICP0 disrupts silencing in epithelial cells during lytic infection include degradation of cellular IFI16, degradation of PML and disruption of PML bodies, and disruption of the repressive HDAC-CoREST-LSD1-REST complex by dissociating HDAC." (PMID 27190217, 2016). "Our recent study using direct imaging approaches for incoming Ad genome complexes showed that neither IFI16 nor PHF13/SPOC1 associates with incoming Ad genomes during immediate early phases of infection." (PMID 27782081, 2016). "Indeed, by immunofluorescence microscopy, we observed colocalization of PML with both full-length IFI16 and its PY domain at early stages of infection." (PMID 27935834, 2016). "Similar to HSV-1 infection, IFI16 assembled at nuclear peripheral foci early in infection." (PMID 27935834, 2016). "The importance of IFI16 in cell regulation and defence from pathogen infection is known." (PMID 27280708, 2016). "To determine whether the cytoplasmic IFI16 detected during KSHV de novo infection and latency represents newly synthesized IFI16 or redistributed from the nucleus, we used 50 nM Leptomycin B (LPT) to block nuclear export to the cytoplasm." (PMID 26134128, 2015). "Interestingly, HSV-1 induces the specific degradation of IFI16 at late times post-infection (after 4 h), dependent, at least in part, on ICP0." (PMID 25375629, 2014). "Our studies suggest that a balance between ICP0 and IFI16 may play a crucial role in determining the outcome of infection." (PMID 25375629, 2014). "In addition, viral gene expression was repressed, somewhat, during infection with this ICP0-null virus in IFI16-positive cells compared with that in IFI16-depleted cells, but viral gene expression of ICP0-competent rescue HSV-1 was not affected." (PMID 25375629, 2014). "Nuclear localization of IFI16 was shown to be essential for recognition of nuclear herpesviral DNA during infection, indicating that HDACs may play a critical role in IFI16-mediated DNA sensing." (PMID 23807710, 2013). "While acetylation of IFI16 is critical for positioning this DNA sensor in the appropriate cellular compartment prior to infection, the roles of IFI16 acetylation and associated HDAC functions during infection require further investigation." (PMID 23807710, 2013). "HSV-1 DNA released during early infection may be recognized by IFI16, resulting in expression of CCL3; while, CXCL10 expression is mediated via an IFI16-independent pathway." (PMID 23062757, 2012). "In addition, we found productive infection to upregulate IFI16 and PAF1 in myeloid cells." (PMID 39798087, 2025).
infection (continued). "In addition, immunoprecipitated IFI16 as well resulted to be enriched in mtDNA following infection." (PMID 39283943, 2024). "The nucleolar population of IFI16 likely contributes to the formation of perinuclear puncta during infection, as we observed an anti-correlation between the fluorescence intensities of IFI16-eGFP in the nucleolus and those at the nuclear periphery upon infection with HSV-1." (PMID 37283074, 2023). "As HSV-1 is known to target IFI16 for degradation, we performed infections with an HSV-1 strain that harbors a mutation in the ring finger (RF) domain of the viral E3 ubiquitin ligase ICP0 and thereby lacks the ability to suppress IFI16 functions (ICP0-RF HSV-1)." (PMID 37283074, 2023). "However, an explanation for these results may again stem from the ability of HSV-1 to downregulation IFI16 and cGAS expression and/or inhibit their signaling pathways in human microglia following infection." (PMID 33042875, 2020). "IFI16 localizes to parental viral genome complexes in the infected cell nucleus at very early times after infection (8, 11, 19, –, 21), and we have hypothesized that IFI16 binds to the input parental DNA and recruits epigenetic silencing factors to the viral genomes." (PMID 30670617, 2019). "Since we observed that H2B associates with IFI16 in the nucleus of uninfected and KSHV infected cells and H2B was also pulled down by KSHV and HSV-1 genome during de novo infection, we next determined whether H2B participates in viral genome recognition by IFI16." (PMID 27764250, 2016). "HSV-1 infection could also induce the activation of IFI16 leading to the formation of the IFI16-ASC (apoptosis-associated speck-like protein containing CARD)-procaspase-1 inflammasome complex and maturation of IL-1β early during infection." (PMID 26952111, 2016). "By contrast, during infection with either WT or ICP0-RF HSV-1, there are several up-regulated lactylation sites in the HIN-200 #2 domain of IFI16, perhaps interfering with its DNA binding ability." (PMID 39772686, 2025). "Then, as viral replication and innate immune signaling proceed during infection with ICP0 RF, by 8 hpi, the interaction profile of SLFN5 remains correlated with IFI16, while those of PML, DAXX, and SP100 diverge to cluster with one another." (PMID 40577456, 2025). "TVs expressing sgRNAs targeting known RFs like TRIM5, IFI16, IFITM2, SAMHD1, GBP5 and IFITM1 were enriched after 15 and 20 days post-infection confirming that targeting RFs provides a selection advantage to the respective viruses." (PMID 38714682, 2024). "Key regulatory genes such as IFI16, IFITM1, and SP100 show exceptionally high degrees of connectivity, indicating their central role in the immediate host response to the infection." (PMID 39591472, 2024). "We found that the type I interferon (IFN-I)-related genes, DDX60, IFI16, IRF7, ISG15, OAS1, and STAT1, were more highly expressed after Omicron breakthrough infection." (PMID 39835127, 2024). "Subsequently, it was reported that IFI16 forms filamentous structures on ICP0 null HSV-1 chromatin, which in turn, drive the deposition of H3K9me3 heterochromatin mark by 6 h post-infection (hpi)." (PMID 38399958, 2024). "Infection with KSHV activates various DNA sensors, including cGAS, STING, IFI16, and DExD/H-box helicases." (PMID 38793630, 2024). "CCL2 and CXCL10 transcripts were upregulated after 30 days and 60 days of infection, as were IFN-a, IFN-b, ISG15, and IFI16 transcripts." (PMID 38737767, 2024). "Studies suggest that IFI16 plays a vital role in antiviral immunity against HSV-1, KSHV, HCMV, HPV and HIV infection." (PMID 37410794, 2023). "As expected, we observed IFI16-GFP puncta localizing at the nuclear periphery, at sites of viral genome deposition, early in infection, i.e. at 1 h post infection (hpi) with ICP0-RF HSV-1." (PMID 37283074, 2023). "Upon siRNA knockdown of CDK2 in IFI16-GFP expressing HFFs, we observed a significant reduction in IFI16 filament formation during infection." (PMID 37283074, 2023).
infection (continued). "IFI16 can induce interferon production early in infection and exert antiviral effects, whereas later in infection, ICP0 targets IFI16 for degradation through its E3 ubiquitin ligase activity and promote virus replication." (PMID 36742325, 2023). "We analyzed cells within developing HSV-1 plaques and assessed IFI16 co-localization with a viral protein marker for viral genomes, ICP4, at both plaque edges (early infection) and plaque interiors (late infection)." (PMID 37283074, 2023). "Our results give a first approximation of IFI16 inflammasome activation during BVDV replication in bovine macrophages; however, more studies are needed to determine its activation mechanism during infection with the ncp-BVDV strain." (PMID 37515181, 2023). "Using ChIP-seq, we probed the interaction between endogenous IFI16 and the HSV-1 genome during infection." (PMID 35575489, 2022). "During the infection process, HHV DNA can be recognized by DNA sensors TLR3/9, STING and IFI16, which are present in the endosome, cytoplasm and nucleus, respectively." (PMID 35337341, 2022). "At early times post-infection of HSV-1, IFI16 recognizes the HSV-1 genome in the nucleus, and then re-localizes into cytoplasm, causing the ASC colocalization." (PMID 35008917, 2022). "Activated IFI16 induced the expression of IFNβ through IRF3 activation and the production of NF-κB-dependent proinflammatory genes during infection with several DNA viruses, including HIV, HSV-1, and VACV." (PMID 34356829, 2021). "IFI16, which is located in the nucleus and has two HIN-200 domains, forms an inflammasome upon infection by viruses such as herpesviruses." (PMID 34177950, 2021). "Our results demonstrated that HPV E7 interacted with the HINB domain of IFI16 and promoted the ubiquitin-proteasome-mediated degradation of IFI16 by recruiting the E3 ligase TRIM21, resulting in the inhibition of cell pyroptosis during infection." (PMID 33061806, 2020). "This indicates that in proinflammatory macrophages, IFI16 and AIM2 are dispensable for HSV-1 induced inflammasome activation early during infection." (PMID 32101570, 2020). "Despite moderate kd efficiencies, reduced IFI16 and PYHIN1 expression increased infectious virus yield of CCR5-tropic HIV-1 AD8, which is capable of spreading infection in macrophages, on average by ~6.4-fold at 3 dpi and ~21.6-fold at 6 dpi." (PMID 32760121, 2020). "POP3, through interactions with AIM2 and IFI16, blocks inflammasome responses induced by infection with dsDNA viruses, including Vaccinia virus (AIM2), CMV (AIM2), and KSHV (IFI16)." (PMID 32962268, 2020). "At late stages of infection, we also found that HCMV is able to promote IFI16 nuclear delocalization through UL97-mediated IFI16 phosphorylation." (PMID 32351486, 2020). "Upon infection with herpes simplex virus 1 (HSV-1) in human fibroblasts, we characterize the contribution of IFI16 oligomerization to downstream protein interactions and antiviral functions, including cytokine induction and suppression of HSV-1 replication." (PMID 31337724, 2019). "By confocal microscopy, we confirmed that endogenous IFI16 and UBTF colocalize in fibroblasts during mock infection and early HSV-1 infection." (PMID 31337724, 2019). "At various times after infection, we performed structured illumination microscopy (SIM) to detect endogenous IFI16." (PMID 30670617, 2019). "Here, we show that IFI16 is in complex with the H3K9 methyltransferase SUV39H1 and GLP and recruits them to the KSHV genome during de novo infection and latency." (PMID 31682228, 2019). "In contrast, infection with less-virulent HSV-1 strains (KOS, RE or F) or with the clinical isolate KOS63 induced a lower expression level of NLRP3 and IFI16 inflammasomes." (PMID 31367214, 2019).
infection (continued). "Having demonstrated that infection with virulent HSV-1 strains increased NLRP3, NLRP12, and IFI16 inflammasome in infected human corneal epithelial cells, we next determined the level of expression of several components downstream of these inflammasomes." (PMID 31367214, 2019). "Cells were harvested at 2, 8, and 24 h post-infection and the level of expression of NLRP3, NLRP6, NLRP12, IFI16, and AIM2 was determined by western blot." (PMID 31367214, 2019). "To visualize the tripartite interaction between IFI16, H3K9 MTase and the KSHV genome in situ, we performed Proximity Ligation Assay (PLA) in TIME cells 24 hr after infection with EdU-labeled KSHV." (PMID 31682228, 2019). "Demonstration of IFI16’s specific interaction with GLP and SUV39H1 and the effect of IFI16 KD upon the recruitment of SUV39H1 and GLP to the KSHV genome during de novo infection." (PMID 31682228, 2019). "In the early phases of infection, HCMV pp65 recruits IFI16 to the major immediate-early promoter (MIEP), stimulating MIEP activity." (PMID 31861809, 2019). "To further assess if IFI16 KD can influence the outcome of KSHV de novo infection, we measured the copy numbers of latent ORF73 and lytic ORF50 mRNAs after IFI16 KD in TIME cells." (PMID 31682228, 2019). "Together, these results suggested that IFI16 is instrumental in recruiting H3K9MTase SUV39H1 and GLP onto KSHV lytic promoters during de novo infection, resulting in deposition of the heterochromatin H3K9me3 mark." (PMID 31682228, 2019). "HSV-1EdU infection of shCtrl or shIFI16 cells demonstrated that both PML and Daxx strongly colocalized with vDNA independently of IFI16." (PMID 29309427, 2018). "As we failed to observe any significant recruitment of IFI16 to infecting HSV-1 genomes under a range of infection conditions, our data suggest that the stable recruitment of PML and IFI16 to infecting viral genomes occurs with temporally distinct kinetics." (PMID 29309427, 2018). "Along with nuclear DNA sensor IFI16, we detected ATRX and PML recruitment to viral DNA by 15 min post infection (mpi), almost immediately upon nuclear entry." (PMID 30465651, 2018). "We used herpes simplex virus with bioorthogonally labeled genomes to detect host factors recruited to viral DNA shortly after its nuclear entry and found that the cellular IFI16, PML, and ATRX proteins colocalized with viral DNA by 15 min post infection." (PMID 30465651, 2018). "We observed that during infection with VACV, endogenous IFI16 relocalized to viral factories in the cytosol, which also contain DNA and the VACV virus protein A3, as visualized during infection with VACV expressing an A3-mCherry fusion protein." (PMID 28194029, 2017). "In contrast, the levels of IFI16, a known degradation substrate of ICP0, were reduced by infection both the wild type and T67A viruses." (PMID 28783105, 2017). "To test this, we knocked-down IFI16 in MDMs and investigated the levels of HIV production 6 days post-infection." (PMID 28186168, 2017). "Nevertheless, these findings demonstrated that similar to de novo infection, latent KSHV infection induces the redistribution of the IFI16-H2B complex to the cytoplasm." (PMID 27764250, 2016). "The expression of PRRs involved in sensing nucleic acids (TLR3 and IFI16) and the NOD-like receptor NLRP9 increased following infection." (PMID 27677841, 2016). "In agreement, we observed IFI16 foci overlap with centromere protein complexes and ICP0 during infection with HSV-1 viruses with functional ICP0 (WT and d106), but not those lacking either ICP0 ubiquitylation activity (RF) or ICP0 expression (d109)." (PMID 27935834, 2016). "The IP results demonstrated that IFI16 and p300 interaction as well as IFI16 and H2B acetylation were inhibited in BRCA1 knockdown cells during KSHV de novo infection." (PMID 27764250, 2016).